CCDC134 (coiled-coil domain containing 134)
Description:
Molecular adapter required to prevent protein hyperglycosylation of HSP90B1: during translation, associates with nascent HSP90B1 and the STT3A catalytic component of the OST-A complex and tethers them to a specialized translocon that forms a microenvironment for HSP90B1 folding. In the CCDC134-containing translocon, STT3A associates with the SRT pseudosubstrate motif of HSP90B1, preventing access to facultative glycosylation sites until folding is completed, preventing hyperglycosylation and subsequent degradation of HSP90B1. In extracellular secreted form, promotes proliferation and activation of CD8(+) T-cells, suggesting a cytokine-like function. May inhibit ERK and JNK signaling activity. May suppress cell migration and invasion activity, via its effects on ERK and JNK signaling. May also localize in the nucleus: enhances stability of the PCAF histone acetyltransferase (HAT) complex member TADA2A and thus promotes PCAF-mediated histone acetyltransferase activity. Has a critical role in the regulation of osteogenesis and bone development.
Synonyms: FLJ22349; OI22
Tractability: Antibody: UniProt places it where antibodies can reach, with high confidence; UniProt predicts a signal peptide or a membrane-spanning region; its Gene Ontology location is reachable by antibodies, with medium confidence. PROTAC: ubiquitination databases record sites on it; its protein half-life has been measured.
Gene: Protein-coding gene on chromosome 22 (41,800,321 to 41,832,172, forward strand). Ensembl gene ENSG00000100147.
Subcellular location: Endoplasmic reticulum lumen; Secreted; Cytoplasm; Nucleus
Subcellular location (Human Protein Atlas): Cytosol; Vesicles; Predicted to be secreted
Gene Ontology:
Molecular function: protein binding; protein-macromolecule adaptor activity
Biological process: positive regulation of MyD88-dependent toll-like receptor signaling pathway; positive regulation of Wnt signaling pathway; regulation of glycoprotein biosynthetic process; regulation of ossification
Cellular component: cytoplasm; cytosol; endoplasmic reticulum lumen; extracellular region; membrane; nucleus
Genetic constraint (gnomAD): Loss-of-function variants: 26 observed, 25.75 expected, observed/expected ratio (o/e) 1.01, 90% interval 0.74 to 1.4. The upper end of that interval is the gene's LOEUF score, 1.4, which puts it in group 5 of 6, group 1 being the genes least tolerant of losing a copy. Missense variants: 259 observed, 300.87 expected, observed/expected ratio (o/e) 0.86, 90% interval 0.78 to 0.95. Synonymous variants: 110 observed, 121.89 expected, observed/expected ratio (o/e) 0.9, 90% interval 0.77 to 1.06.
Homologues: Orthologues: chimpanzee CCDC134 (99% identical), macaque CCDC134 (99% identical), dog CCDC134 (93% identical), pig CCDC134 (93% identical), guinea pig CCDC134 (91% identical), rat Ccdc134 (91% identical), rabbit CCDC134 (91% identical), mouse Ccdc134 (90% identical), tropical clawed frog ccdc134 (65% identical), zebrafish CCDC134 (61% identical), Caenorhabditis elegans F56A8.9 (26% identical).
Diseases named in the same sentence as CCDC134 in open-access papers:
CCDC134 is named in the same sentence as 15 diseases in open-access papers, as found by Europe PMC text mining. Sharing a sentence is not in itself a finding about the gene and the disease. The quoted sentences say what the papers report.
gastric cancer (5 papers, 2015 to 2024). A primary or metastatic malignant neoplasm involving the stomach. "Our sequencing results show that CCDC25 may also affect PI3K and MAPK pathways, research has shown that the CCDC family gene CCDC134 can suppress the progression of gastric cancer by inhibiting the MAPK pathway." (PMID 38570766, 2024). "CCDC134 regulates cell migration and invasion and may be a therapeutic target for gastric cancer." (PMID 35311121, 2022). "The MAPK/ERK pathways have been shown to play a role in controlling gastric cancer cell migration and invasion induced by IL-22, PRL3, NAIF1, and CCDC134." (PMID 37817112, 2023).
osteogenesis imperfecta (3 papers, 2022 to 2025). Osteogenesis imperfecta (OI) comprises a heterogeneous group of genetic disorders characterized by increased bone fragility, low bone mass, and susceptibility to bone fractures with variable severity. "Recently, CCDC134 loss-of-function mutations were identified in osteogenesis imperfecta patients." (PMID 39656203, 2025). "Studies have shown that CCDC134 is a novel gene involved in severe progressive deformation recessive osteogenesis imperfecta (type III)." (PMID 35311121, 2022).
breast carcinoma (2 papers, 2022 to 2024). "In order to study the diagnostic value of CCDC134 in distinguishing breast cancer samples from normal breast cancer, ROC curve analysis was conducted." (PMID 35311121, 2022). "In breast cancer, upregulated CCDC134 is significantly associated with lower survival and immune infiltrates invasion." (PMID 35311121, 2022). "We further evaluated the diagnostic and prognostic value of CCDC134 in breast cancer and its correlation." (PMID 35311121, 2022). "Our study suggests that overexpression of CCDC134 in breast cancer is associated with lower survival." (PMID 35311121, 2022). "ROC curve analysis indicated that CCDC134 may be a promising diagnostic biomarker for differentiating breast cancer from normal tissues." (PMID 35311121, 2022). "Thirdly, besides CCDC134, there might be other novels genes associated with breast cancer." (PMID 35311121, 2022). "We hypothesized that CCDC134 levels were associated with breast cancer survival." (PMID 35311121, 2022). "Secondly, in vitro and in vivo experiments need to be designed in order to further study the detailed mechanism of CCDC134 affecting immune invasion of breast cancer." (PMID 35311121, 2022). "The results showed that CCDC134 protein expression in breast cancer was significantly higher than that in normal tissues." (PMID 35311121, 2022). "HPA immunohistochemical staining also showed up-regulation of CCDC134 protein expression in breast cancer tissues." (PMID 35311121, 2022). "In this study, we found that CCDC134 mRNA and protein expression were up-regulated in breast cancer tissues." (PMID 35311121, 2022). "The RFS of patients with high level CCDC134 breast cancer was shorter than that of patients with low level CCDC134 breast cancer (57.27 months vs. 36.96 months, P = 2.0E-6)." (PMID 35311121, 2022). "Previous studies supported abrine, Benzo(A) Pyrene, bisphenol A, Soman, Sunitinib, Tetrachloroethylene, and Valproic Acid can target CCDC134 in vitro and is expected to make new progress in the treatment of breast cancer." (PMID 35311121, 2022). "Paired data analysis also showed that mrna expression level of CCDC134 in breast cancer tissues (n = 112) was significantly higher than that in adjacent normal tissues (n = 112) (3.351±0.597 vs 2.998±0.617, P <0.001)." (PMID 35311121, 2022). "The expression of CCDC134 in breast cancer tissues was significantly higher than that of CCDC134 mRNA expression in adjacent normal tissues." (PMID 35311121, 2022). "Using Kaplan-Meier curves and univariate analysis, we confirmed that CCDC134 expression is associated with short RFS and that CCDC134 can serve as a potential biomarker of poor prognosis in breast cancer." (PMID 35311121, 2022). "Our study suggests that CCDC134 can serve as a biomarker of poor prognosis and a potential immunotherapy target in breast cancer." (PMID 35311121, 2022). "We downloaded the transcription profile of CCDC134 between breast cancer and normal tissues from the Cancer Genome Atlas (TCGA)." (PMID 35311121, 2022). "Based on our data, we conclude that CCDC134 can serve as a biomarker for poor prognosis in breast cancer." (PMID 35311121, 2022). "Furthermore, the findings demonstrated that upregulating CCDC134 hindered the motility and invasion of breast cancer." (PMID 38468244, 2024). "Therefore, we evaluated the prognostic role of CCDC134 in breast cancer and its correlation with immune invasion." (PMID 35311121, 2022). "Furthermore, according to kaplan-Meier curves and log-rank tests, breast cancer patients with high mRNA expression had lower survival rates than those with low CCDC134 levels." (PMID 35311121, 2022). "In this study, we found that CCDC134 is up-regulated in breast cancer." (PMID 35311121, 2022). "In summary, in this study, we found for the first time that CCDC134 is highly up-regulated in breast cancer, and poor prognosis can be used as a potential prognostic marker and may play a specific role in immune infiltration." (PMID 35311121, 2022).
breast carcinoma (continued). "To test this hypothesis, we evaluated the prognostic role of CCDC134 in breast Cancer based on data from the Cancer Genome Atlas (TCGA)." (PMID 35311121, 2022). "In addition, CCDC134 may play a specific role in immune invasion of breast cancer." (PMID 35311121, 2022). "The relationship between CCDC134 mRNA expression and RFS in breast cancer patients was explored by Kaplan-Meier curve." (PMID 35311121, 2022). "The correlation analysis between CCDC134 expression and immune cell infiltration in breast cancer has not been studied." (PMID 35311121, 2022). "However, in breast cancer, CCDC134 expression and its prognostic value have not been fully studied." (PMID 35311121, 2022).
Arthritis (1 paper, 2025). Inflammation of a joint. "Conversely, transgenic mice overexpressing CCDC134 were protected in encephalomyelitis and arthritis models." (PMID 39656203, 2025).
cervical carcinoma (1 paper, 2025). A carcinoma arising from either the exocervical squamous epithelium or the endocervical glandular epithelium. "Another example is CCDC134 which was identified to be associated with pharynx cancer and cervical carcinoma both in EA and AA." (PMID 41358317, 2025).
melanoma (1 paper, 2023). A malignant, usually aggressive tumor composed of atypical, neoplastic melanocytes. "To investigate the role of CCDC134 in T cell-mediated anti-tumor immunity, we assessed Ccdc134 TKO mice in the B16-OVA murine melanoma model." (PMID 37234153, 2023).
cancer (5 papers, 2022 to 2025). A tumor composed of atypical neoplastic, often pleomorphic cells that invade other tissues. "CD8+ T cells are central components for cancer immunity, and our finding that Ccdc134 deficiency inhibits CD8+ T cell activation suggested a potential role of CCDC134 in regulating antitumor immunity." (PMID 37234153, 2023). "The expression of Coiled-Coil Domain Containing 134(CCDC134) is up-regulated in different pan-cancer species." (PMID 35311121, 2022). "CCDC134 was significantly upregulated in 14 of the 18 cancers compared with normal tissue." (PMID 35311121, 2022). "The co-essential relationships between HSP90B1, CCDC134 and OST-A across the DepMap panel of >1000 cancer cell lines are likely a consequence of their shared role in IGF1 signaling, known to be a universal driver of cell growth and survival." (PMID 39509507, 2024). "CCDC134, STT3A and OSTC showed a strong signature of genetic co-essentiality with each other and the LRP6 chaperone HSP90B1 in the Cancer Dependency Map (DepMap)." (PMID 39509507, 2024).
tumor (4 papers, 2015 to 2023). "Correlation analysis showed that CCDC134 mRNA expression was associated with tumor purity immune invasion." (PMID 35311121, 2022). "We analyzed the correlation between CCDC134 expression and six types of tumor-infiltrating immune cells in the TIMER database." (PMID 35311121, 2022). "Here we further identify that Ccdc134 deficiency accelerates TCR downmodulation by ubiquitinating CD3ε and its downstream pathways following TCR activation, rendering mice refractory to T cell-mediated inflammatory and anti-tumor responses." (PMID 37234153, 2023). "Through tumor Immune Estimation Resource (TIMER) and tumor Immune System Interaction database (TISIDB) to determine the relationship between CCDC134 expression level and immune infiltration." (PMID 35311121, 2022). "Compared to WT mice, Ccdc134 TKO mice had significantly increased tumor progression and tumor size." (PMID 37234153, 2023). "More importantly, effector CD8+ T cells producing IFN-γ and granzyme B were significantly reduced in tumors and draining lymph nodes from Ccdc134 TKO mice, relative to WT mice, and Ccdc134 TKO CD8+ T cells expressed lower levels of Ki67 than WT controls in the tumor microenvironment." (PMID 37234153, 2023). "We have previously shown that CCDC134 as a potential member of the γc cytokine family significantly augmented the activation, proliferation, and cytotoxicity of CD8+ T cells in vitro and recombinant hCCDC134 protein exerted anti-tumor activity in a CD8+ T cell-dependent manner in vivo." (PMID 37234153, 2023).
adenocarcinoma (1 paper, 2022). A common cancer characterized by the presence of malignant glandular cells. "The results suggest that CCDC134 may be a promising biomarker for differentiating adenocarcinoma tissue from normal tissue." (PMID 35311121, 2022).
CCDC134 also shares sentences with these, for which no sentence is quoted: Ehlers-Danlos syndrome (1 paper); encephalomyelitis (1); esophageal cancer (1); lung carcinoma (1); Pan (1); pharynx cancer (1).